CD4 (CD4 molecule)
Diseases named in the same sentence as CD4 in open-access papers (continued):
Sharing a sentence is not in itself a finding about the gene and the disease.
infection (continued). "The slope of 3.6 in naive cells suggests that for every increase in the infection rate of the naive compartment, there was a corresponding approximately 4-fold increase in the infection rate of the total CD4 compartment." (PMID 34228640, 2021). "These sheltered particles make it possible for direct cell-to-cell infection of uninfected macrophages and CD4+ T cells in the same region as infected macrophages, which provides an evolutionary advantage for macrophages as cellular reservoirs." (PMID 33897659, 2021). "Several HIV-1 proteins, including Nef, Vpu, and Env, down-regulate CD4 expression in macrophages to avoid super-infection." (PMID 34233649, 2021). "CRF55_01B infection was associated with slower loss of CD4 count than CRF01_AE (13.6 vs. 23.3 [cells/μl]1/2/year, P < 0.05)among MSM with initial CD4 count of 200–350 cells/μl." (PMID 34399785, 2021). "The analysis comparing PRE to memory CD4+ T cells also revealed memory subsets that were preferentially spared from infection, including CXCR3−CCR4−cells in vivo and Tcm, Tfh, Th17, Th2, and CXCR3−CCR4−cells in vitro." (PMID 33910003, 2021). "We postulate that in mucosal fibroblasts, diminished cell-associated HA levels improve cellular contact between the fibroblasts and CD4+ T cells, thereby increasing the efficiency of trans-infection." (PMID 33976386, 2021). "Depletion of CD4 TRM cells significantly impaired clearance of a primary or secondary infection of the nose with B. pertussis." (PMID 33976385, 2021). "As the rapid decreasein the CD4/CD8 ratio indicated successful infection with EBV, the histology of theknee joint tissues of mice was analyzed." (PMID 33793647, 2021). "CD4 TRM cells accumulate in the nasal tissue during infection with B. pertussis and these are predominantly IL-17 producing, with a small number secreting IFN-γ or both cytokines." (PMID 33976385, 2021). "Altogether, these data indicate that older adult Bp cases show features of CD4+ T-cell Bp-specific immunosenescence following clinical infection, highlighted by significantly lower cytokine and proliferative responses than younger adolescent counterparts." (PMID 35822011, 2021). "A recent pre-print report from a Brazilian research group describes infection of CD4+ T cells by SARS-CoV-2, with subsequent high expression of IL-10 by infected cells." (PMID 33493185, 2021). "Due to their important roles in infection, many conserved sites (such as the CD4 and coreceptor binding sites) within these variable regions are rarely, if ever, directly occluded from immunological access via glycans." (PMID 33669676, 2021). "A significantly higher reduction in bacillary counts of ΔhisD was observed 48 h post infection following stimulation with CD4 T cells as compared to un-stimulated macrophages." (PMID 33767335, 2021). "The duration of infection at the time CD4 T cell counts are measured in the chronic steady state is typically not known in untreated individuals." (PMID 33542308, 2021). "Representative flow gating of tetramer positive cells showed that infection induced a substantial increase in T. gondii and flagellin specific CD4+ T cell frequencies in the LP compartment." (PMID 34597344, 2021). "A main effect of early antiviral Rb treatment and diminished viral replication following LCMV-Cl13 infection was the rescue of CD4 T cell function." (PMID 34206262, 2021). "(A) Spike-specific CD4+ T cells from convalescent vaccinated individuals harbor higher proportions of Tn and Tcm cells and lower proportions of Ttm cells than those from infection-naïve vaccinated individuals." (PMID 34636722, 2021). "(D) tSNE dot plot of spike-specific CD4+ T cells from infection-naïve and convalescent individuals after second dose of vaccination, demonstrating the segregation of the cells from the two groups of patients." (PMID 34636722, 2021).
infection (continued). "While B-cell responses and NAbs to SARS-CoV decline significantly 1–2 years after infection, induction of memory CD4+ T-cells is suggested to confer more durable protection." (PMID 34239884, 2021). "Here the authors compare antibodies, cytokines and immune cell responses in adults and children over 6 months post-infection showing, among other things, a reduced CD4+ and CD8+ T cell response in children." (PMID 34326343, 2021). "Upon MCMV infection, effector CD4 T cells infiltrate the SGs after approximatively one week of infection, where they form discrete clusters." (PMID 34959486, 2021). "At day 3 post infection, CD4 T cells in the uGT constituted 10.3% of all cells in the SIM group, compared to 3.9% in the SC group." (PMID 34925371, 2021). "Marek’s disease virus (MDV), an avian alphaherpesvirus, infects chickens, transforms CD4+ T cells, and induces immunosuppression early during infection." (PMID 35003129, 2021). "In contrast, individuals initiated on ART during chronic infection presented with CD4+ T cell decline, with counts significantly lower compared to the uninfected controls at both 1-month (p=0.004) and 12-months (p=0.0002) post-infection." (PMID 34630420, 2021). "A recent study in Trypanosoma cruzi demonstrated a significant reduction in IFN-γ+ CD4+ T cells in the spleens and lymph nodes of μMT mice, compared to normal mice, following infection." (PMID 34663097, 2021). "In another murine model of VL, the infection-induced IFN-γ secreting CD4+ T cells are related to damage to bone marrow function." (PMID 33680991, 2021). "The crucial roles of CD4+ cells during B. microti infection are also demonstrated experimentally since treatment of mice with anti-CD4 MAbs diminished protection against challenge infection." (PMID 34414129, 2021). "Both IL-21 and IL-6 are important for generating Tfh CD4+ T cells that are selected for during LCMV Cl 13 infection." (PMID 34696381, 2021). "In sheep from trial 2, CD4+ T cells represented 35.74%, 31.18% and 35.34% of cells in uninfected, early-stage infected and late-stage of infection, respectively." (PMID 34215335, 2021). "Nevertheless, virus-specific CD8 T cell exhaustion and deletion still occur at early time points post-infection despite the presence of CD4 T cells (albeit with attenuated function themselves)." (PMID 34206262, 2021). "Specifically, the proportion of Th1 cells increased from 14.0% of CD4+ T cells at baseline to 26.1% at 2 weeks post-infection." (PMID 33959105, 2021). "The remaining five convalescent donors, by contrast, never exhibited a robust T cell response, and in fact after full vaccination actually exhibited a highly significantly lower CD4+ T cell response than the infection-naïve vaccinees." (PMID 34636722, 2021). "In Bl-Eng2- and Advax3-vaccinated mice, we found a significant, strong correlation between the number of single- and double-cytokine (IFN-γ and IL-17)-producing, Bl-Eng2-specific CD4+ T cells in the lung after infection and the reduction in lung CFU." (PMID 34399628, 2021). "These cells transfer captured HIV-1 to target CD4+ T cells that come into contact with them, which leads to virus transmission that is more efficient than infection by cell-free virus." (PMID 34696365, 2021). "And in fact, brain tissue of chronically infected TKO mice showed increased TNF and IFNγ as well as increased production of these cytokines released by CD4+ T cells in the chronic phase of infection." (PMID 33968021, 2021). "The percentages and total numbers of CD4+CD25+Foxp3+ T cells diminished within three weeks of infection." (PMID 34869064, 2021). "Colonic biopsies were collected prior to infection to provide baseline CD4+ T cell data, 28 days after infection to determine effects on mucosal CD4+ T cell depletion, and at 70 days after infection to evaluate effects of MSC treatment." (PMID 34014838, 2021). "The percentages of CD4+ T cells after infection were slightly increased in the two groups of animals." (PMID 34625475, 2021).
infection (continued). "As MHCII+ AT2s are present at the site of infection with access to both antigen and antigen-specific CD4+ T cells, it is possible that AT2s help to deliver this second checkpoint." (PMID 34183650, 2021). "CCL20 attracts CCR6+ cells such as dendritic cells (DCs) and CD4+ TH17 cells that migrate along the CCL20 gradient to the site of infection." (PMID 33659876, 2021). "One patient developed PCP nine months after CAR-T-cell therapy, with a CD4+ count of 44 cells/μL at the time of infection." (PMID 33672208, 2021). "These three pathways also showed the greatest change in CD4+ T cells between the early infection and chronic infection stages." (PMID 34603402, 2021). "As expected, the gp350-specific CD4+ T-cell clone used in the validation experiments responded strongly to B-cells at the earliest timepoint sampled, one day post infection." (PMID 34882759, 2021). "In contrast, studies reported that CD8+ cells were recruited into the trachea earlier than CD4+ cells after infection with virulent 793B or live attenuated IBV vaccine or a combination of live attenuated vaccine with a booster dose of an inactivated vaccine." (PMID 34822646, 2021). "In this context, where the host efficiently controls virus replication and spread, Ifnar1-/- and WT CD8 and CD4 T cells responded similarly to the infection as determined by CFSE dilution." (PMID 34015056, 2021). "(C) tSNE contour heatmaps of spike-specific CD4+ T cells from infection-naïve and convalescent individuals, after first and second dose vaccinations, highlighting the phenotypic differences between the two groups of patients." (PMID 34636722, 2021). "The inflammatory process of cardiac injury in CCC is mainly mediated by CD4+ T cells as they play a central role in controlling specific effectors functions in infection." (PMID 34289913, 2021). "And indeed, we found significantly reduced frequencies of CD4+ Tregs in brains of TKO mice compared to WT mice in the chronic phase of infection." (PMID 33968021, 2021). "In PBMC samples from pediatric VL, the frequency of IL-9+CD4+T cells was higher during infection, which gradually decreased upon the treatment, thereby implying the role of these cells in VL pathogenesis." (PMID 33680991, 2021). "Infection begins with the binding of envelope gp120 to the CD4 T-cell receptor (TCR), and then also to a coreceptor, most commonly either the CCR5 or CXCR4 seven transmembrane G-protein coupled chemokine receptor." (PMID 34960781, 2021). "Notwithstanding, adult B. malayi antigen (BmA) influenced HIV-1 trans-infection of CD4+ T cells in vitro." (PMID 34603287, 2021). "Individuals initiating treatment during chronic infection also had significantly lower CD4+ T cell counts compared to hyperacute treated individuals at 1-month (p=0.014) and at 12-months (p=0.001) post-infection." (PMID 34630420, 2021). "More recently, it has been shown that increased numbers of activated CD4+ T cells are present within the HLN of cattle at 13 weeks post-infection, but these cells are poorly responsive to re-stimulation with F. hepatica antigen suggesting T cell exhaustion." (PMID 34215335, 2021). "Y-axes are labeled to match the corresponding y-axes for spike-specific T cell responses in panel B. (D) The CD4+ T cell response is boosted by the second vaccine dose to a greater extent in infection-naïve than convalescents individuals." (PMID 34636722, 2021). "Containments of the infection are mediated by cytokines and the interaction between macrophages and T lymphocytes (CD4 and CD8)." (PMID 33070259, 2021). "CD4+T cells are important during the acute phase of infection, whereas CD8+T cells play a crucial role in the clearance of infection during the chronic phase." (PMID 34386011, 2021). "Our generalization incorporated four possible mechanisms of action of the anti-α4β7 antibody: increased viral clearance, virus neutralization, protection of CD4+ T cells from infection, and increased antigen presentation." (PMID 34106916, 2021).
infection (continued). "infection, CD4 T cells are sufficient to induce the penetration of parasites into the brain parenchyma and can stimulate the production of immune molecules required for parasite and T cells brain invasion." (PMID 34587172, 2021). "Specifically, we identified a unique population of CD4+/CD8+ double positive T cells (DP T cells) that upregulated inflammatory cytokines such as TNF-⍺ as well as Granzyme B over the course of infection." (PMID 34929014, 2021). "PBMCs collected from SHIV.CH505.375H-infected RMs at the peak of viremia (week 2 post-infection) were used as the source of target SHIV-infected RM CD4+ T cells." (PMID 34484212, 2021). "A higher relative increase in effector CD4+ T cells was observed in gonadal AT, with significant accumulation from day 14 post-infection onwards, showing a 14.6-fold increase by day 28 post-infection." (PMID 34525131, 2021). "Another study identified HIV-infected immune cells in mechanically disaggregated human tonsillar tissue after in vitro infection as expressing CD4 (T cells), CD11c (dendritic cells), or CD68 (monocytes)." (PMID 34372518, 2021). "During the rapid rise in CD4+ T cell numbers, inflammation in the previous infection site recurs and the patients develop a recurrence of previous symptoms, most often without evidence of reinfection." (PMID 33923792, 2021). "If low numbers of specific CD4+ T cells are expected (immunocompromised patients, long time since infection/vaccination) the number of analyzed cells should increase up to 300000." (PMID 34910301, 2021). "While CD4+ T cell depletion is one of the major hallmarks of HIV infection, infection with HIV also results in the depletion of M. tuberculosis-specific CD4+ and CD8+ T cells." (PMID 34295314, 2021). "Despite lower expansion rates and total numbers, CD4+ T cell help seems to be required to tackle the infection in humanized mice since CD4+ T cell depletion prior to infection results in higher viral loads." (PMID 33833760, 2021). "Subsequently, CD4+ T-helper cells support the production of specific antibodies by B cells and promote the bactericidal activity of phagocytes that together clear the infection." (PMID 34708062, 2021). "When it comes to bacterial clearance of STM infection, however, there is consensus that a CD4+ T-cell response is vital." (PMID 34451970, 2021). "Early studies have proven that the CD4 receptor is necessary for viral attachment and infection, so our studies focused on CD4+ T cell subsets." (PMID 34960667, 2021). "Our study therefore reveals that antigen expression kinetics regulates CD4 T cell differentiation during infection and establishes a link between in vivo antigen expression, T cell differentiation, and vaccine protective capacity." (PMID 33879592, 2021). "We constructed the CD4+ T cell-specific Ctnnb1 conditional knockout mice and infected the mice with Mtb H37Rv through aerosol infection." (PMID 33628846, 2021). "An increase in the number of T cells and CD4/CD8-positive cells indicates an enhanced ability to protect against infection." (PMID 34867392, 2021). "Even with low IFN-I levels later during LCMV Cl 13 infection, virus-specific CD4+ T cells appear to respond to IFN-I signals." (PMID 34696381, 2021). "In general, EMT CD4+ T cells were less permissive to DFV-B infection; however, the ratio of mC cells to total infected cells (mC+DP) steadily increased from 15.7% (day 0 infection) to 64.8% (day 10 infection)." (PMID 33835029, 2021). "Macrophages were reported to engulf HIV-1-infected CD4+ T cells, a process that leads to their own infection, but the capture recognition signals remained unclear." (PMID 34425695, 2021). "Across the cohort, HIV infection of CD4 T cells measured at day 3 post-infection ranged from 1.08 to 15.16% (median: 5.1%)." (PMID 34276657, 2021).
infection (continued). "Infection of naïve cells and of their cell precursors (CD4+ thymocytes, CD34+ multipotent hematopoietic progenitor cells) within these organs has been put forward to explain why X4 viruses deplete CD4TL more than R5 viruses." (PMID 33872329, 2021). "We did not observe any difference in the numbers of CD4+ and CD8+ T cells after 2 weeks of infection but did detect a dramatic decrease in number of CD4+ T cells after 8 weeks of infection." (PMID 33923025, 2021). "By contrast, the proportions of specific effector memory CD4+ T-cells were significantly lower, whereas specific effector CD4+ T-cells were higher after infection than after vaccination." (PMID 34960185, 2021). "In wild-type mice, the overall frequency of CD4+ T cells out of CD90+ cells was unaffected by the vaccination in the early phase of infection with Mtb, whereas a higher proportion of CD4+ T cells had an activation phenotype in vaccinated mice." (PMID 34351501, 2021). "Latent infection is accomplished by integrating HIV-1 into transcriptionally silent regions of the genome of quiescent CD4+ T cells." (PMID 34198973, 2021). "Nevertheless, it was also demonstrated Pdl1-/- mice infection with L. major induced lower frequencies of a population of CD4+Ly6Chi effector T cells and higher frequencies of Foxp3+ Tregs compared with WT mice." (PMID 33776999, 2021). "Here, we showed that infection of HIS-NSG mice strongly induced the differentiation of naïve CD4+ and CD8+ T-cells into effector memory cells." (PMID 34685494, 2021). "Ratios of CD38+ HLA-DR– CD4+ (P = 0.0027)/CD8+ (P = 0.0373) T-cell subsets in the SS phase were significantly higher than in SN before infection." (PMID 34349746, 2021). "Seven days after infection, the expansion of CD4+ T cells was determined in the spleen, lungs, and salivary glands." (PMID 33459589, 2021). "HIV, for example, attaches to DC-SIGN via high-mannose residues on gp120 glycans and uses DCs as shuttles, allowing the trans-infection of neighboring CD4+ T cells." (PMID 34638920, 2021). "Infected cells were analyzed by two-color flow cytometry at 48 h (cell lines) or 96 h (primary CD4 T cells) post-infection to measure the frequency of latent cells versus cells that support HIV-1 gene expression." (PMID 34469717, 2021). "Based on our previous findings, where the mumps-specific CD4/CD8 T cell ratio was higher after vaccination than after natural infection, MuV vaccination seems to induce relatively more CD4+ than CD8+ T cells." (PMID 34211021, 2021). "CD4+ iNKT cells were depleted faster and more profoundly than conventional CD4+ T cells, and the preferential infection of CD4+ iNKT cells over conventional CD4+ T cells was confirmed by in vitro infection experiments." (PMID 34753817, 2021). "The enhanced ability to clear the infection in long-term convalescent mice was reflected in a significantly higher number of B. pertussis specific IL-17-producing CD4+ TRM cells in the nasal cavity 7 days after challenge." (PMID 33976385, 2021). "We confirmed that lung CD4+ T cells in our Il13−/− mouse strain expressed eGFP in lieu of functional IL-13 after infection with N. brasiliensis when compared with controls." (PMID 34127548, 2021). "These were used to infect a lymphocytic cell line CEM.NKR.CCR5 which showed substantial downregulation of CD4 and >30% infection of the cells as determined through p24 expression compared to a mock infection." (PMID 34566999, 2021). "Surprisingly, given that IL-21 is paradigmatically mainly produced by CD4+ cells, we have found IL-21 expression in B cells during the experimental infection." (PMID 35071041, 2021). "We conclude that AM-derived HIV isolates are T-tropic and can enter macrophages through contact with an infected CD4+ T cell, which results in productive infection of AMs." (PMID 33594125, 2021). "Here, we report that, in contrast to HIV-1, HTLV-1 induces M-Sec expression in CD4+ T cells, and M-Sec contributes to efficient cell-to-cell infection of HTLV-1." (PMID 34843591, 2021).